CXCL12 (C-X-C motif chemokine ligand 12)
Diseases named in the same sentence as CXCL12 in open-access papers (continued):
Sharing a sentence is not in itself a finding about the gene and the disease.
adenoma (5 papers, 2014 to 2022). A neoplasm arising from the epithelium. "This process would be initiated early in colonic carcinogenesis since CXCL12 expression is already lost at the adenoma stage." (PMID 35406582, 2022). "In contrast, we showed that CXCL12 expression is strongly decreased in 94% of adenomas and 85% and 75% of MSI and MSS carcinomas, respectively." (PMID 35406582, 2022). "The expression of CXCL12 can be increasing from healthy mucosa to adenomas and adenocarcinomas or, on the contrary, decreasing." (PMID 35406582, 2022). "The level of CXCL12 transcript was also significantly decreased in adenomas (p = 2.2e−36), which indicated an early event in the pathological sequence." (PMID 28418886, 2017). "Both MSI and MSS tumors and adenomas expressed 4-fold less CXCL12 than unpaired normal tissues and this difference was significant (p < 1e−16)." (PMID 28418886, 2017). "Overall, CXCL12 expression was decreased in 94% (44/47) of the adenomas, 85% (64/75) of the MSI carcinomas and 75% (335/444) of the MSS tumors." (PMID 28418886, 2017). "CXCL12 induced a statistically significant increase in DNA synthesis in the majority (65%) of the adenoma tested." (PMID 25484899, 2014). "CXCL12 is overexpressed in pituitary cells where it can directly influence adenoma formation, through autocrine mechanisms resulting in constitutive CXCR4 activation." (PMID 25484899, 2014). "Likewise, other studies suggest an association between CXCL12/CXCR4 expression and the induction of adenomas, carcinomas, and the development of metastases." (PMID 35406582, 2022). "As observed for CXCL12, loss of PCAF was found in adenomas as well as in MSS and MSI tumors." (PMID 28418886, 2017). "Interestingly, in few adenomas, the blockade of CXCR4 with AMD3100, a known CXCR4 antagonist, caused, beside the abolishment of CXCL12-mediated increase in cell proliferation, also a reduction of basal DNA synthesis." (PMID 25484899, 2014). "We confirm a reduced expression of CXCL12 in 75% of MSS carcinomas and show that the decrease is an early event as already present in adenomas." (PMID 28418886, 2017). "Therefore, the better characterization of CXCR4/ACKR3/CXCL12 axis in PAs could pave the way for novel pharmacological approaches, especially for those adenoma subtypes (i.e., TSH and ACTH-secreting tumors, as well as NFPA) still waiting for efficacious therapeutic drugs." (PMID 26441831, 2015). "Several mechanisms by which CXCL12/CXCR4 modulates pituitary function and promotes adenoma cell proliferation and their target as potential therapeutic approach have been suggested." (PMID 25484899, 2014). "The CXCL12 expression in adenomas did not significantly differ by distinct histological subtype or degree of dysplasia." (PMID 28418886, 2017). "Recently, several studies have revealed the expression of CXCL12 and/or CXCR4 in human pituitary tumors, suggesting that this chemokine may act as a promoting factor for adenoma development." (PMID 26441831, 2015). "However, the majority of studies focused on the analysis of CXCL12 and CXCR4 expression in human neoplastic pituitary tissues and their role in adenoma cell proliferation." (PMID 25484899, 2014). "However, CXCL12 effects of on cell proliferation were directly evaluated in vitro on a small number of primary cultures of adenoma cell derived from GHoma, NFPA, and ACTH-secreting adenomas." (PMID 25484899, 2014). "The staining of CXCL12, CXCR4, and FAPα was more intense in high-grade dysplastic epithelial cells and intramucosal invasive LARC cells than in the non-neoplastic epithelial cells of the 16 adenoma cases (p < 0.001 for each)." (PMID 34976180, 2022).
amyotrophic lateral sclerosis (5 papers, 2022 to 2024). Amyotrophic lateral sclerosis (ALS) is a neurodegenerative disease characterized by progressive muscular paralysis reflecting degeneration of motor neurons in the primary motor cortex, corticospinal tracts, brainstem and spinal cord. "Based on CSF results, we decided to evaluate the diagnostic ability of CXCL12 levels in plasma, a more accessible biofluid, and compare to NF-L’s accuracy to differentiate between HC and amyotrophic lateral sclerosis patients." (PMID 39188590, 2024). "To calculate the diagnostic accuracy of CSF CXCL12 in discriminating between HC and amyotrophic lateral sclerosis cases, we estimated the corresponding AUC value." (PMID 39188590, 2024). "To calculate the diagnostic accuracy of plasma CXCL12 in discriminating between HC and amyotrophic lateral sclerosis cases, we estimated the corresponding AUC value." (PMID 39188590, 2024). "Similarly, to calculate the diagnostic accuracy of CSF NF-L and compare to CXCL12’s accuracy in discriminating between HC and amyotrophic lateral sclerosis cases, we estimated the corresponding AUC value." (PMID 39188590, 2024). "In the present study, we are aimed to unveil CXCL12’s potential in the differential diagnosis of conditions mimicking amyotrophic lateral sclerosis symptoms and compare its capacity with the current gold standard, the CSF NF-L levels." (PMID 39188590, 2024). "While NF-L is altered in many pathologies, CXCL12’s specificity underscores its relevance in amyotrophic lateral sclerosis pathophysiology and its potential utility in differential diagnosis of the disease." (PMID 39188590, 2024). "To compare differential diagnosis ability between CSF CXCL12 levels and CSF NF-L levels, we also calculated the AUC values for NF-L in the same cohort of amyotrophic lateral sclerosis patients and amyotrophic lateral sclerosis–mimic disorders." (PMID 39188590, 2024). "In our study, we contributed to this goal by quantifying CSF CXCL12 levels of amyotrophic lateral sclerosis patients and comparing them with those of HCs and patients with amyotrophic lateral sclerosis–mimicking diseases." (PMID 39188590, 2024). "T-test indicated a significant increase when comparing plasma levels of CXCL12 in amyotrophic lateral sclerosis cases (2022 ± 81.8 pg/mL) to HC cases (1739.43 ± 77.3 pg/mL; P = 0.015)." (PMID 39188590, 2024). "In plasma, single molecule array (SIMOA) neurofilament light chain determination [amyotrophic lateral sclerosis (86.00 ± 12.23 pg/mL) versus healthy control (12.69 ± 1.15 pg/mL); P = 0.000] was more accurate than plasma C-X-C motif chemokine ligand 12 (area under the curve 0.98 ± 0.01405)." (PMID 39188590, 2024). "Furthermore, we validated the assessment of plasma CXCL12 levels in amyotrophic lateral sclerosis, providing a cost-effective and non-invasive alternative suitable for broader use, particularly in serial collections." (PMID 39188590, 2024). "However, to test the potential capacity of CSF CXCL12 levels to differentiate between amyotrophic lateral sclerosis and amyotrophic lateral sclerosis–mimic cases, we also estimated the corresponding AUC values for each biomarker." (PMID 39188590, 2024). "CXCL12 exerted protective anti-inflammatory effects in Alzheimer’s disease (e.g. promoting microglial phagocytosis of amyloid beta plaques) but attracted pro-inflammatory microglia involved in the disease onset and progression of amyotrophic lateral sclerosis (ALS)." (PMID 36725964, 2023). "The lack of paired plasma samples of amyotrophic lateral sclerosis–mimic disorders does not allow us to define the capability of CXCL12 in the differential diagnosis of amyotrophic lateral sclerosis, only amyotrophic lateral sclerosis diagnosis, and neither compare it with NF-L." (PMID 39188590, 2024).
aneurysm (5 papers, 2009 to 2025). Bulging or ballooning in an area of an artery secondary to arterial wall weakening. "Thus, the Cxcl12–Cxcr4/Ackr3 axis may play pivotal roles in the initiation, development, and progression of aneurysm." (PMID 40440080, 2025).
basal cell carcinoma (5 papers, 2009 to 2022). A carcinoma involving the basal cells. "Among the CXCL chemokines, CXCL-12/SDF-1 was previously associated with the rejection of metastatic melanoma during IL-2 therapy and together with CXCL-9 through -11 chemokines in association with the rejection of basal cell carcinomas (BCCs) treated with TLR7 agonists." (PMID 19583830, 2009). "CXCL12 has been reported to increase IL‐6 expression in fibroblasts and human basal cell carcinoma, while AMD3100 inhibits the CXCL12‐induced IL‐6 expression." (PMID 35363937, 2022). "Moreover, a study-using laser capture microdissection revealed CXCL12 and CXCL14 to be upregulated in stroma of prostate and basal cell carcinomas." (PMID 28178651, 2017). "Interestingly, CXCL12 can increase the RNA and protein level of the CXCR4 receptor in basal cell carcinoma and PC3 cells." (PMID 22074556, 2011).
bladder (5 papers, 2014 to 2023). "Former researches also showed that CXCL12/CXCR4 axis could regulate bladder carcinogenesis via activating extracellular signal-regulated kinase (ERK), which was subject to TXNIP negative regulation." (PMID 33747959, 2021). "Moreover, luciferase assays and quantitative polymerase chain reaction (qPCR) were used to study how chemokines CXCL11 and CXCL12 regulate androgen-regulated genes (ARGs) in LNCaP prostate-tumor cells." (PMID 25884570, 2015). "Moreover, by single-cell sequencing, our team verified that CXCL12, a T-lymphocyte proliferation regulator, influenced bladder oncogenesis and progression by depleting T-lymphocyte proliferation in the tumor microenvironment, thus promoting tumor immune evasion." (PMID 36211359, 2022). "Here we show that, in the LNCaP prostate-tumor cell line, androgens coordinate the expression of CXCR4 and CXCR7, thereby promoting CXCL12/CXCR4-mediated cell motility." (PMID 25884570, 2015).
chondrosarcoma (5 papers, 2010 to 2018). A malignant cartilaginous matrix-producing mesenchymal neoplasm arising from the bone and soft tissue. "Interestingly, chondrosarcoma cell invasion is increased by hypoxia-induced expression of CXCR4 and MMP1, a process mediated by HIF1α and ERK, and CXCL12, also called SDF-1, increases the invasiveness of chondrosarcoma cells." (PMID 21647363, 2011).
colorectal tumor (5 papers, 2014 to 2025). "Furthermore, HIF-2α-containing exosomes from primary colorectal tumor cells promoted CXCL12 secretion by peritumoral fibroblasts through HIF-2α binding to the CXCL12 promoter, which in turn induced M2 macrophage accumulation and tumor cell invasion." (PMID 40756343, 2025). "In summary, the present study showed that the expression of CXCL12 mRNA is higher in rectal tumours and CXCR4 mRNA was inversely correlated in colorectal tumours with a lymphatic invasion." (PMID 29887884, 2018). "Our study demonstrates that both the chemokine ligand CXCL12 and its receptor CXCR4 are expressed by colorectal tumour cells." (PMID 29887884, 2018). "However, other mechanisms are most likely responsible for tumor progression and dissemination, and the interaction between CXCL12 and its receptor CXCR4 was shown to play a major role in the settlement of colorectal tumor cells in the liver." (PMID 24629239, 2014).
cystitis (5 papers, 2008 to 2023). Inflammation of the urinary bladder. "Our lab examined the expression and therapeutic effect with receptor blockade of the chemokine CXCL12, and one of its two receptors, CXCR4, in a rodent model of cystitis." (PMID 24738044, 2014).
dementia (5 papers, 2014 to 2023). Loss of intellectual abilities interfering with an individual's social and occupational functions. "Associations between the tested biomarkers (CXCL12, CX3CL1, YKL-40, Ng, and NPTXR), cognitive status, and neurochemical dementia biomarkers of AD were compared." (PMID 37685973, 2023). "Taken together, our results highlight a general mechanism that is needed to combat dementia, in which the CCR2/CCL2 axis, together with additional chemokines, such as Cxcl12, regulate the communication pathway between the brain and the immune system." (PMID 34172073, 2021).
diabetic foot ulcers (5 papers, 2021 to 2026). "In acute wounds, CXCL12 expression levels are markedly upregulated, whereas in chronic wounds, similar to diabetic foot ulcers, CXCL12 was found to be downregulated resulting in disturbed endothelial progenitor cell homing and delayed wound healing." (PMID 34683890, 2021).
experimental autoimmune encephalomyelitis (5 papers, 2011 to 2025). An autoimmune demyelinating disease of the central nervous system that is produced experimentally in animals by the injection of homogenized brain or spinal cord in Freund's adjuvant. "The inflammation observed in the CNS of MS patients and of mice with experimental autoimmune encephalomyelitis (EAE) is associated with increased expression of the C-X-C motif chemokine 12 (CXCL12)." (PMID 26747276, 2016). "In a previous study, CXCL12 promoted the differentiation of Tregs and increased IL-10 expression in an experimental autoimmune encephalomyelitis model by TCR-stimulated human T cells." (PMID 40309773, 2025). "Evidence also indicates that CXCL12 can promote the repair of myelin sheaths in the CNS in experimental autoimmune encephalomyelitis (EAE)." (PMID 37008218, 2023). "Both in MS and in experimental autoimmune encephalomyelitis (EAE), the deleterious CNS inflammation has been associated with upregulation of CXCL12 expression in the CNS." (PMID 26747276, 2016). "Evidence has shown that the NPC migration through white matter in experimental autoimmune encephalomyelitis was also based upon the CXCL12/CXCR4 signaling." (PMID 24771246, 2015). "Using the murine MS model, experimental autoimmune encephalomyelitis (EAE), we previously demonstrated that antagonism of the chemokine receptor CXCR7 blocks endothelial cell sequestration of CXCL12, thereby enhancing the abluminal localization of CXCR4-expressing leukocytes." (PMID 22145790, 2011).
Immunodeficiency (5 papers, 2012 to 2022). Failure of the immune system to protect the body adequately from infection, due to the absence or insufficiency of some component process or substance. "Although we cannot dismiss the hypothesis that the WS immunodeficiency eventually affects anti-HPV immune responses, we rather favor the possibility that the CXCL12/CXCR4 axis represents a host susceptibility factor for HPV-infection and associated carcinogenic evolution." (PMID 23009155, 2012).
intrahepatic cholangiocarcinoma (5 papers, 2015 to 2025). A carcinoma that arises from the intrahepatic bile duct epithelium in any site of the intrahepatic biliary tree. "In intrahepatic cholangiocarcinoma, higher expression of CXCL12 is associated with metastasis and poor prognosis." (PMID 32632106, 2020). "In addition, knockdown of the receptor of CXCL12, namely, CXCR4, downregulated mesenchymal markers including Slug in intrahepatic cholangiocarcinoma." (PMID 34118928, 2021).
ischemic disease (5 papers, 2015 to 2024). Lack of blood supply to an area of the body, resulting in impairment of tissue oxygenation. "In this condition, spheroids grew faster than monolayer culture and, focusing the attention on the treatment of the ischemic disease, the authors found increased expression levels of survival factors (CXCL12 and HIF‐1a) in response to the size of the spheroids." (PMID 36209478, 2022). "MSC-derived CXCL12 niche played an important role in the development of EPCs and enhanced the efficiency of EPC therapy for ischemic diseases." (PMID 33579354, 2021).
Lewis lung carcinoma (5 papers, 2014 to 2021). "Specific EP3- or EP4-receptor agonists (ONO-AE-248 and ONO-AE1-329) stimulated CXCL12 expression by mice fibroblasts in vitro, whereas EP3- or EP4-receptor deficiency reduced stromal expression of CXCL12/ C-X-C motif chemokine receptor 4 in mice implanted with Lewis lung carcinoma cells." (PMID 32962984, 2020). "Tumor-derived CXCL12 was shown to attract tumor-promoting myeloid CD11b+ cells in a mouse model of Lewis lung carcinoma." (PMID 25526031, 2014).
lymphopenia (5 papers, 2014 to 2024). Reduction in the number of lymphocytes. "Our findings support a dysregulation of the CXCL12/CXCR4 chemotaxis of T-helper lymphocytes in HHT patients, potentially linked to their T-helper lymphopenia and susceptibility to infection." (PMID 34906163, 2021). "We provide several elements supporting an alteration in the CXCL12/CXCR4 axis on T-helper lymphocytes in HHT patients, possibly related to their specific infectious risk and T-helper lymphopenia." (PMID 34906163, 2021). "Therapeutic administration of ACT-1004-1239 or siponimod, given at doses leading to clinically relevant pharmacodynamic effects, namely maximal plasma CXCL12 increase and maximal lymphopenia over 24 h, respectively, demonstrated similar efficacy on EAE clinical scores and relapse rate." (PMID 38819698, 2024). "Disruption of CXCL12/CXCR4 signaling is also a key step in HSC mobilization by G-CSF.This lead us to suspect a causative role of CXCR4/CXCL12 in the lymphoid progenitors rebound during the profound lymphopenia observed after allo-HSCT." (PMID 24621606, 2014). "We believe that, in the absence of aGVHD, low CXCL12 levels favor proliferation and egress of committed progenitors from the BM as part of a regenerative mechanism to correct for lymphopenia." (PMID 24621606, 2014).
mesothelioma (5 papers, 2015 to 2023). A usually malignant and aggressive neoplasm of the mesothelium which is often associated with exposure to asbestos. "CXCL12 addition to coculture of mouse mesothelioma tumor cells and bone marrow derived macrophages leads to the phagocytosis of a substantial fraction of tumor cells." (PMID 35565443, 2022). "Chemokine signals that attract monocytes in mesothelioma include CCL2, CCL4, CCL5, and CXCL12 and these appear to be of mesothelioma cell origin." (PMID 31867277, 2019). "CXCR4 was found in almost all mesotheliomas (97%) and CXCL12 in 78%; another receptor, CXCR7, was only weakly expressed." (PMID 26078352, 2015). "Most of our experiments were performed on a mouse mesothelioma model using BoxA, a fragment of HMGB1 that, like CXCL12, engages CXCR4 and induces its internalization together with CD47." (PMID 35565443, 2022). "Mesothelioma cells attract monocytes in the TME though releasing some chemokines, such as chemokine (C-C motif) ligand 2 (CCL2), chemokine (C-C motif) ligand 4 (CCL4), chemokine (C-C motif) ligand 5, and C-X-C motif chemokine ligand 12 (CXCL12)." (PMID 38259475, 2023). "In cell culture experiments, Li and co-workers could also demonstrate that CXCL12, the sole ligand of CXCR4, can induce proliferation in mesothelioma which can be antagonized by administration of CXCR4 inhibitors such as AMD3100." (PMID 29228566, 2017).
metastasis (5 papers, 2013 to 2023). The spread or migration of cancer cells from one part of the body (where they first appeared) to another. "Upregulation of CXCR4 is accepted to be indicative of shorter overall survival and related to an elevated risk of developing lymph node and liver metastasis via the interaction with CXCL12, which can further promote angiogenesis and the formation of new blood and lymphatic vessels." (PMID 35163198, 2022).
nephritis (5 papers, 2013 to 2026). Inflammation of renal tissue. "CXCL12 is produced constitutively in the peritoneal cavity, spleen, and glomeruli of mice with nephritis." (PMID 39070795, 2024). "In NZB/W mice, antagonists of CXCL12 or IL-10 are used early in life to prevent autoantibodies, nephritis, and mortality." (PMID 39070795, 2024). "The administration early in life of a mouse monoclonal antibody that displays CXCL12 antagonist activity prevented the development of autoantibodies, nephritis, and death in (NZBxNZW)F1 mice." (PMID 34744730, 2021). "Various studies have shown that CXCL12 levels are elevated in the kidneys of older mice with nephritis, and that neutralization of CXCL12 with a monoclonal antibody at an early age can prevent the development of proteinuria and prolong the survival." (PMID 31024553, 2019).